NLRP3 (NLR family pyrin domain containing 3)
Diseases named in the same sentence as NLRP3 in open-access papers (continued):
Sharing a sentence is not in itself a finding about the gene and the disease.
Stroke (continued). "Of importance, TXNIP, a redox-regulated protein, can bind to and activate the NLRP3 inflammasome in response to the oxidative stress associated with stroke, and when TXNIP is inhibited, Nrf2 acts as a negative regulator of the NLRP3 inflammasome." (PMID 31998437, 2020). "NLRP3 inflammasome inhibition improves cognitive dysfunction in diabetic rats following stroke." (PMID 32425784, 2020). "This indicates that NEK7 might activate NLRP3 via activating microtubule acetylation after stroke, which requires further investigation." (PMID 32733353, 2020). "Therefore, inhibition of pathways upstream of NLRP3 inflammasome can be a promising strategy to develop new therapies for stroke and HI." (PMID 33034416, 2020). "The critical roles of the NLRP3 inflammasome during stroke have been documented in many studies." (PMID 31920554, 2019). "Some studies have reported that the NLRP3 inflammasome is involved in the activation of M1 microglia after stroke, and the conversion processes of procaspase-1 to caspase-1 also contributes to the production and secretion of M1 typed mature pro-inflammatory cytokines." (PMID 31920554, 2019). "We then examined whether meisoindigo impacted NLRP3 inflammasome activation and M1–M2 shift after stroke, and whether TLR/NF-κB signaling pathway participated in the anti-inflammation and neuro-protective effect of meisoindigo." (PMID 31920554, 2019). "The NLRP3 inflammasome is an important factor in inflammatory injury after stroke, but whether it is the leading factor for deteriorating diabetic-stroke remains an unanswered question." (PMID 31174550, 2019). "In addition, NLRP3 inflammasome activity contributed to cigarette smoke-induced exacerbation of stroke severity." (PMID 31787973, 2019). "NLRP3 deficiency in mice, treatment with the NLRP3 inflammasome inhibitor MCC950/CRID3, and intracerebroventricular injection of NLRP3 siRNAs all ameliorated clinical outcomes in experimental models of stroke." (PMID 31015277, 2019). "Therefore, we postulated that NLRP3 inflammasome activation contributes to cigarette smoke-induced exacerbation of stroke injury." (PMID 31787973, 2019). "MCC950 ameliorated deficits in hippocampal-dependent memory after diabetic-stroke in rats, through inhibition of the NLRP3 inflammasome with decreased IL-1β expression, lower blood-brain barrier permeability, and reduced cell death of the neurons in the CA1 and DG regions of the hippocampus." (PMID 31174550, 2019). "NLRP3 inflammasome activation following stroke is established in earlier studies to contribute to stroke injury through the pro-inflammatory cytokines (e.g. IL-1, IL-18) as well as the pleiotropic effects of cleaved caspase-1 in mediating pyroptosis and apoptosis." (PMID 29654318, 2018). "Consistent with earlier report demonstrating reduced NLRP3 inflammasome activation coincident with neuroprotective modulations, these findings support our presumption that inhibition of NLRP3 inflammasome is the key effector of TXNIP ablation as well as stroke induced injury." (PMID 29654318, 2018). "Providing supportive evidence for NLRP3 involvement in acute injury following stroke, these findings further suggest that NLRP3 inflammasome may represent a promising imminent target to develop newer therapeutics." (PMID 29654318, 2018). "However, there is still no specific evidence stating the relationship between mitochondria and NLRP3 inflammasomes in stroke." (PMID 30153825, 2018). "One study found that the expression of NLRP3 was increased in the brain tissue of stroke patients." (PMID 30618576, 2018). "The NLRP3 inflammasome has been proved to express in diversity of cells such as microglia, astrocyte, neuron, and endothelial cell and in different kinds of diseases such as traumatic brain injury, stroke, brain tumor, neurodegenerative disease, and others." (PMID 27652274, 2016).
Stroke (continued). "Recently, it has been shown that A151, a synthetic oligodeoxynucleotide containing multiple telemeric TTAGGG motifs, reduces ischemic brain damage and NLRP3 mRNA levels in Stroke-Prone Spontaneously Hypertensive rats submitted to permanent middle cerebral artery occlusion." (PMID 27127546, 2016). "Interestingly, these authors showed that intravenous immunoglobulin treatment protected brain cells in experimental stroke models by a mechanism involving suppression of NLRP3 activity." (PMID 27127546, 2016). "Moreover, caspase-1 activation was completely blunted in ASC-deficient or AIM2-deficient, but not in cGAS-deficient, NLRP1-deficient or NLRP3-deficient, BMDMs in response to stimulation with serum from stroke mice or stimulation with DNA." (PMID 39112714, 2024). "Because studies have shown that preventive inhibition of NLRP3 inflammasome can maintain its early therapeutic effect into the subacute phase, inhibition of NLRP3 inflammasome in the acute phase of CI directly affects inflammation in the ischemic penumbra after stroke." (PMID 39139639, 2024). "MCC950, a specific inhibitor of the NLRP3 inflammasome, inhibits NLRP3 activation mainly by interacting with the Walker B motif in the NACHT structural domain of NLRP3 and by affecting the ATP hydrolysis of NLRP3, thereby reducing cell death, and may be considered a candidate for stroke treatment." (PMID 37165005, 2023). "Activation of NLRP3 inflammasomes through NF-κB and MAPK signaling pathways to secrete pro-inflammatory cytokines after brain ischemia may be an intrinsic mechanism that enlarges the ischemic damage and causes the disorder of glucose metabolism after stroke." (PMID 36950100, 2023). "In a study investigating the effects of curcumin on white matter damage after stroke, the use of AAV‐mediated NLRP3 knockdown was found to reduce pyroptosis‐related protein levels in the peri‐infarct area of mice 21 days after ischemia–reperfusion, alleviating the post‐stroke white matter lesions." (PMID 37551863, 2023). "Therefore, the cellular source of NLRP3 may vary significantly according to distinct pathologies, such as migraine, permanent or transient cerebral ischemia, as well as the process of stroke-induced brain damage." (PMID 37822799, 2023). "To investigate whether Notch1 plays the role as a regulatory hub during the acute phase of cerebral ischemia–reperfusion injury and whether it affects neuronal pyroptosis after stroke, we examined the protein expression of Notch1 and NLRP3 in the ischemic penumbra of mice on day 3 after MCAO." (PMID 38137105, 2023). "The suppression of NLRP3 obviously reduces cerebral ischemic injury, protecting against neuronal cell death in both in vivo and in vitro settings, which may be an effective strategy for treating stroke." (PMID 37101593, 2023). "HIF-1α may be an NLRP3 inflammasome regulator in curcumin administration during stroke cases." (PMID 37915409, 2023). "Indeed, FPR1 signaling is important in activating the NLRP3 inflammasome as evidenced by reduced inflammation, leukocyte infiltration, and tissue damage in Fpr-1 KO mice, as well as limiting neuroinflammation following stroke." (PMID 35603196, 2022). "Targeting NLRP3 might be a novel choice for the prevention and recovery of stroke." (PMID 36204568, 2022). "Many aspects of the biology of NLRP3 inflammasome in stroke remain, however, unknown." (PMID 35115638, 2022). "Hence, a study on the various components of the NLRP3 inflammasome molecular pathway may give beneficial findings on stroke recovery and brain repair." (PMID 35328506, 2022). "Therefore, in NLRP3-KO mice, the degree of lung injury was reduced with the improvement of stroke, which may be due to two reasons." (PMID 35432726, 2022). "Furthermore, NLRP3 inflammasome activation after stroke may be related to the induction of cytokine storm-related proinflammatory cytokines, which can be relieved by Rux via its targeting of the JAK2/STAT3 pathway." (PMID 34367186, 2021).
Stroke (continued). "Therefore, we hypothesized that curcumin reduced NLRP3 inflammasome-mediated microglial pyroptosis probably through inhibition of the NF-κB pathway after stroke." (PMID 34630845, 2021). "NLRP3-induced inflammation plays a detrimental role in systemic endothelial dysfunction (e.g., large vessel disease, arteriosclerosis), but the role of endothelial NLRP3 induction in stroke and its impact on BBB integrity is largely unknown." (PMID 34930895, 2021). "Moreover, extracellular ASC specks, which might originate from the first stroke-affected area, were shown to contribute to the aggravation of recurrent stroke in NLRP3-dependent manner." (PMID 32635451, 2020). "However, whether the NLRP3 inflammasome is involved in the neuroprotective effect of Gen against reproductively senescent stroke remains to be confirmed." (PMID 32625078, 2020). "Therefore, treatments aiming at NLRP3 upstream and downstream signaling pathways may provide new strategies for treating stroke." (PMID 32581721, 2020). "Hence, targeting pathways upstream and downstream of NLRP3 inflammasome signaling may offer substantial promise in developing new therapeutics for stroke." (PMID 27652274, 2016). "Indeed, the expression pattern of the NLRP3 inflammasome in primary cortical neurons subjected to simulated ischemia, in a mouse model of focal ischemic stroke, and in brain tissue samples from stroke patients has been described." (PMID 27127546, 2016). "By blocking NLRP3 activation, MCC950 can improve stroke outcomes in a mouse model of transient middle cerebral artery occlusion (tMCAO)." (PMID 40075143, 2025). "Therefore, we hypothesized that the NLRP3 inflammasome could play a key role in stroke damage." (PMID 39753298, 2025). "NLRP3 inhibition with MCC950 will improve NVU remodeling and cognitive outcome following stroke via vagotropic uncoupling between endothelial cells and hippocampal neurons." (PMID 40741047, 2025). "In this study, we examined the expression patterns of the AIM2 inflammasome and other cytoplasmic PRRs, including NLRP1a, NLRP3, and NLRC4, in mice after stroke and found that AIM2 and NLRP3 were activated 7 days after cerebral ischemia." (PMID 39854137, 2025). "Earlier studies demonstrated that inhibition of the NLRP3 inflammasome is the primary reason for diminishing TXNIP and stroke-induced injury." (PMID 40272769, 2025). "These dual mechanisms—suppression of NLRP3-driven neuroinflammation and enhancement of BDNF-mediated neuroplasticity—highlight the critical role of aerobic exercise in post-stroke rehabilitation." (PMID 40256392, 2025). "Our study also showed that CX3CR1 gene deletion inhibited the expression of NLRP3, ASC, caspase‐1, IL‐1β, IL‐18, and NF‐κB p65 protein after stroke." (PMID 38421089, 2024). "In T2DM mice, stroke induced earlier and higher TLR4, NLRP3, and cytokine expression (SAA, IL1β, IL6, TNFα) in the liver compared to heart and kidney, as measured by Western blot." (PMID 36968490, 2023). "Its exact mechanism of action on NLRP3 is unknown; however, its ability to effectively block NLRP3 activation and reduce the synthesis of the pro-inflammatory factor IL-1β has allowed its use for painful strokes and makes it a promising treatment option for stroke." (PMID 37165005, 2023). "Functionally, immediate treatment with the NLRP3-specific inhibitor MCC950 ameliorated infarct growth during I/R and improved functional outcome within the first 24 h after stroke onset." (PMID 36600259, 2023). "Next, we investigated the influence of stroke and EPO-administration on the activation of the inflammasomes NLRP3, NLRC4 and AIM2, and their downstreaming cascade." (PMID 34628598, 2022). "In conclusion, NLRP3 inhibition can protect the BBB from rt-PA-induced damage and thereby potentially increase the narrow time window for safe thrombolysis in stroke." (PMID 35453512, 2022).
Stroke (continued). "We also observed a decrease in phosphorylated p65 (p-p65) (an NF-κB factor) in NLRP3-KO-MCAO mice, suggesting that the NF-κB pathway was involved in the protective effect of NLRP3 gene knockout on stroke-induced lung injury." (PMID 35432726, 2022). "TAK1 is reported to regulate the activation of the NLRP3 inflammasome but little is known about the influence of TAK1 on NLRP3, NLRC4, and AIM2 inflammasomes after stroke." (PMID 34628598, 2022). "Many glial inflammasomes have been identified after stroke, and the most widely studied inflammasome is the NOD-like receptor family pyrin domain containing 3 (NLRP3), which is mainly released by microglia after SAH." (PMID 35401398, 2022). "Inhibiting NLRP3 can significantly downregulate downstream inflammatory molecules to reduce neuronal injury/BBB disruption and stroke severity, and therefore, improve neurological outcomes." (PMID 35937062, 2022). "It is therefore promising that the acute treatment with NLRP3 inhibitors such as MCC950 does not only lessen the neuroinflammation in IS and improve the post-stroke neurologic outcome but also reduce the incidence of AD after IS." (PMID 34930895, 2021). "Conclusively, we showed that the receptors of NLRP3, NLRC4, and AIM2, the executors of Caspase-1 and−11 were the main contributors of-post stroke inflammasome activation, which participated in the production of IL-1β, IL-18, and GSDMD." (PMID 33967935, 2021). "To measure the significance of NLRP3-mediated pyroptosis in neuropathology and functional recovery after stroke, we next assess white matter damage and sensorimotor functional recovery after MCAO in NLRP3-shRNA knockdown mice." (PMID 34630845, 2021). "Inhibiting NLRP3 activation induced by ERS can protect neurons from ischemic injury and thus exert a neuroprotective effect after stroke." (PMID 34059091, 2021). "Activation of TXNIP/NLRP3 inflammasome convert pro-caspase-1 into cleaved-caspase-1 and inhibits the TRX resulting oxidative stress in acute HG suture stroke model." (PMID 34681207, 2021). "Meanwhile, compared to the stroke and stroke+PBS group, Ki20227 administration downregulated the expression of NLRP3, active caspase 1, and NF-κB protein in the ischemia penumbra of Ki20227 treatment group mice." (PMID 32908485, 2020). "Comparable results showed an elevated expression of NLRP3 inflammasome components and downstream effector targets in conjunction with NLRP1 in mouse and human brain tissue compromised by stroke." (PMID 32635451, 2020). "To understand the anti-stroke mechanism of QKL, we determined the protein expression levels of NLRP3, ASC, pro-caspase-1, cleaved-caspase-1, pro-IL-1β and cleaved-IL-1β in the brain tissue of rats." (PMID 31747940, 2019). "Expression levels of NLRP3 and NLRP1, as well as cleavage products of caspase‐1, IL‐1β, and IL‐18, were shown to be elevated in postmortem brain tissue of stroke patients." (PMID 31015277, 2019). "The novel compound MCC950, an inhibitor of the NLRP3 inflammasome, has been shown to play a neuroprotective role via specific inhibition of NLRP3-induced ASC oligomerization in stroke." (PMID 31920554, 2019). "The present data shows that specific NLRP3 inflammasome inhibition by MCC950 alleviates infarct size, edema, hemorrhage and behavioral deficits in suture MCAO model of stroke." (PMID 29654318, 2018). "Surprisingly, genetically ablating the NLRP3 inflammasome, which is activated by intracellular cholesterol crystals, had little impact on cytokine production or the MMP response to stroke." (PMID 30417081, 2018). "WT, NLRP3-/-, CD36-/-, and OPN-/- mice underwent DH stroke and were killed 24 h later for determination of acute infarct size." (PMID 30417081, 2018). "Similarly, pharmacological inhibition of the NLRP3/caspase-1 pathway reduces infarct volume and preserves BBB integrity across several preclinical stroke models." (PMID 41408503, 2025).
Stroke (continued). "3‐HKA treatment resulted in a significant decrease in the mRNA level of AIM2 following stroke but had no obvious effect on NLRP3." (PMID 39854137, 2025). "This oxidant appears to simultaneously trigger NLRP3 activation and matrix metalloproteinase (MMP) pathways, thereby amplifying BBB breakdown, accelerating HT formation and worsening outcomes in hyperglycaemic stroke patients." (PMID 41408503, 2025). "Additionally, studies have shown that in rats with thalamic hemorrhage-induced central post-stroke pain (CPSP), around the thalamic injury area, the expression of NLRP3 is significantly increased with microglia and astrocytes activation." (PMID 40083546, 2025). "Although we verified that CMI could potentiate the detrimental effect of recurrent stroke through trained immunity in NLRP3-dependent manner, it is still unclear how CMI influenced the PT stroke in the contralateral side." (PMID 38216560, 2024). "Furthermore, the reports have shown that inhibition of NLRP3 inflammasome alleviates hypoxic endothelial cell death and protects BBB integrity in murine stroke and traumatic brain injury models." (PMID 39764140, 2024). "The activation of the NLRP3 inflammasome in 12/15-LOX-positive cells may contribute to the inflammatory response and neural damage observed in stroke." (PMID 37822799, 2023). "The NLRP3 inflammasome drives the inflammatory response after the transient intermediate phase of IRI and NLRP3 inflammasome continues to drive neuroinflammation within the subacute stroke phase." (PMID 37125240, 2023). "Patients suffering stroke and TBI are found to have a higher level of trimethylamine N-oxide (TMAO) (138, –, 140), which activates various pro-inflammatory responses including NLRP3 inflammasome, MAPK, and NF-κB pathways, predicting higher severity and risk." (PMID 37768071, 2023). "Quercetin has been shown to inhibit the activation of NF-kB and NLRP3 inflammasome by activating the AMPK signaling pathway, which may have potential therapeutic implications for stroke." (PMID 37047299, 2023). "Activation of NLRP3 inflammasomes is highly dependent on ASC recruitment of free procaspase-1 and NLRP3 activation; therefore, targeted inhibition of ASC could also be a therapeutic strategy for stroke." (PMID 37165005, 2023). "For example, increased levels of AMPK following a stroke can inhibit microglial activation and reduce neutrophil infiltration into brain tissue, and AMPK attenuates hippocampal glutamate neurotoxicity by inhibiting ER stress-mediated TXNIP/NLRP3 inflammasomes." (PMID 38069134, 2023). "In this study, we report for the first time that stroke in T2DM mice induces earlier and higher inflammatory factor, cytokine, and acute phase response protein expression such as SAA, NLRP3, IL-1β, IL-6, TNFα, and TLR4 in the liver compared to heart and kidney." (PMID 36968490, 2023). "The expression of NLRP3, ASC, and cleaved-caspase-1 significantly elevated at 6 h post-stroke (* p < 0.05, ** p < 0.01 vs. Sham group), while IPC treatment could partially reverse it (#p < 0.05 vs. pMCAO group)." (PMID 37371374, 2023). "While the role of the NLRP-3 inflammasome in non-sterile NETosis formation has been described in other models, such as adult stroke, little is known about sterile inflammatory conditions in neonatal HI." (PMID 36835009, 2023). "To address this issue, we focused on the long-term outcome after inhibition of the NLR family pyrin domain containing 3 (NLRP3) inflammasome, that has recently been proven to play a central role in the control of inflammatory mechanisms in stroke during I/R injury." (PMID 36600259, 2023). "AIM2 is an inflammasome that is highly expressed in neurons after stroke and, unlike the NLRP3 inflammasome, is only activated by cytoplasmic dsDNA." (PMID 37165005, 2023).